SHCBP1 (SHC binding and spindle associated 1)
Diseases named in the same sentence as SHCBP1 in open-access papers (continued):
Sharing a sentence is not in itself a finding about the gene and the disease.
ovarian carcinoma (1 paper, 2025). A malignant neoplasm originating from the surface ovarian epithelium. "Recent findings reveal that SHCBP1 also suppresses autophagic cell death by activating the AKT/mTOR pathway in ovarian cancer." (PMID 41009347, 2025). "In ovarian cancer, SHCBP1 overexpression induces cisplatin resistance by activating AKT/mTOR signaling and inhibiting autophagic cell death." (PMID 41009347, 2025). "Combined targeting of SHCBP1 and use of an autophagy inhibitor sensitizes ovarian cancer cells to cisplatin treatment." (PMID 41009347, 2025).
paraganglioma (1 paper, 2023). A benign or malignant neoplasm arising from paraganglia located along the sympathetic or parasympathetic nerves. "Finally, SHCBP1 expression was elevated (P<0.05) in paraganglioma (PCPG), kidney renal clear cell carcinoma (KIRC), and skin cutaneous melanoma (SKCM)." (PMID 36920183, 2023).
Splenomegaly (1 paper, 2025). Abnormal increased size of the spleen. "We also found that tumorigenesis associated with G600 cells resulted in splenomegaly, which was reversed by the disruption of either Smyd3 or Shcbp1." (PMID 40157910, 2025).
uterine corpus endometrial carcinoma (1 paper, 2023). A endometrial carcinoma (disease) that involves the body of uterus. "Amongst various human cancers, the alteration frequency of SHCBP1 (>5%) is highest in uterine corpus endometrial carcinoma (UCEC), in which “mutation” accounts for the primary proportion of alterations." (PMID 36920183, 2023).
viral infection (1 paper, 2023). "SHCBP1 is closely related to embryonic development, growth factor signal transduction, cytokinesis, spermatogenesis, tumorigenesis, and viral infection." (PMID 38005336, 2023).
cancer (28 papers, 2016 to 2025). A tumor composed of atypical neoplastic, often pleomorphic cells that invade other tissues. "Emerging evidence indicates that SHCBP1 drives several hallmark features of cancer, including sustained proliferation, apoptotic resistance, invasion, metastasis, and resistance to therapy." (PMID 41009347, 2025). "Increasing evidence from transcriptomic and proteomic analyses in various cancers indicates that elevated SHCBP1 expression is strongly linked to aggressive clinicopathological traits and poor patient prognoses." (PMID 41009347, 2025). "SHCBP1 is commonly overexpressed in diverse cancers, with elevated expression levels strongly associated with more aggressive tumors and unfavorable patient prognosis." (PMID 41009347, 2025). "In further support of this regulatory mechanism, a pan-cancer analysis revealed that elevated SHCBP1 expression is significantly associated with increased copy number alterations and reduced DNA methylation of the SHCBP1 gene." (PMID 41009347, 2025). "Studies in PDAC highlight the diagnostic value of SHCBP1, demonstrating that tissue expression can distinguish cancers from benign pancreatic lesions with high sensitivity and specificity." (PMID 41009347, 2025). "Thirdly, although we have verified the expression of SHCBP1 in several cancers, the exact molecular mechanisms underlying its mechanisms in cancer still require investigation." (PMID 36920183, 2023). "The results revealed that TMB was positively associated with SHCBP1 expression in 18 types of cancers while negatively correlated in THYM and ESCA." (PMID 36920183, 2023). "In addition, another study revealed that SHCBP1 was markedly expressed in GC tissues and was linked to cancer progression and a bad prognosis for patients." (PMID 40657397, 2025). "We conducted a genetic alteration analysis to study SHCBP1 mutations in human cancers." (PMID 36920183, 2023). "Our results indicate that elevated SHCBP1 expression is associated with unfavorable prognosis in different cancers and may be a promising biomarker for accurate diagnosis and treatment." (PMID 36920183, 2023). "In addition, EPIC, MCPCOUNTER, and TIDE algorithms were used to assess the association between cancer-associated fibroblast infiltration and SHCBP1 expression in 33 kinds of cancers." (PMID 36920183, 2023). "Moreover, TMB was positively associated with SHCBP1 expression in 18 types of cancers." (PMID 36920183, 2023). "In addition, cancer-associated fibroblasts cells may play a vital role in modulating SHCBP1 expression." (PMID 36920183, 2023). "Another investigation identified SHCBP1 as one of 11 hub genes contributing to cancer progression and prognosis through comprehensive PPI network and functional enrichment analysis." (PMID 41009347, 2025). "Subsequently, to examine the relationship between SHCBP1 and cancer functional states at a single-cell level in TNBC, we analyzed the GSE77308 cohort via the CancerSEA database." (PMID 40799237, 2025). "Its elevated expression across diverse cancer types, as well as its regulation at transcriptional, post-transcriptional, and post-translational steps, positions SHCBP1 as a potential modulator of various aspects of cancer biology." (PMID 41009347, 2025). "Beyond these major tumor types, SHCBP1 also exhibits significant prognostic potential in additional cancers." (PMID 41009347, 2025). "Emerging evidence highlights the involvement of SHCBP1 in cancer progression across various malignancies." (PMID 40799237, 2025). "Validation of these drug–SHCBP1 interactions and assessments of their therapeutic efficacy in cancer growth remains necessary using in vitro and in vivo models in future studies." (PMID 41009347, 2025). "Taken together, SHCBP1 emerges as a compelling, yet inherently challenging, therapeutic target across diverse cancers." (PMID 41009347, 2025). "Accumulating evidence indicates that SHCBP1 is involved in promoting apoptotic resistance in various cancer types." (PMID 41009347, 2025).
cancer (continued). "These pathways were more closely related to cancer epithelial cells with high SHCBP1 expression, further supporting the tumorigenic role of SHCBP1." (PMID 40799237, 2025). "This review comprehensively explores the molecular features of SHCBP1, its regulatory networks, and its multifaceted roles in cancer progression." (PMID 41009347, 2025). "Elevation of SHCBP1 is confirmed in cancer tissue relative to matched normal controls and is markedly linked to adverse patient survival." (PMID 41009347, 2025). "These examples confirm the key role played by SHCBP1 in various cancer types and emphasize its importance in the study of cancer as a molecular target." (PMID 40657397, 2025). "This compound exhibited anti-cancer effects by downregulating SHCBP1 mRNA expression and subsequently diminishing the interaction between SHCBP1 and β-catenin." (PMID 41009347, 2025). "By analyzing the mRNA expression of SHCBP1 in human pan-cancer tissues, we found that SHCBP1 mRNA expression was also significantly upregulated in many other cancer tissues." (PMID 40799237, 2025). "Together, these data identify SHCBP1 as an important mediator of diverse tumor suppressor networks, enabling cancer cells to advance by simultaneously inhibiting multiple growth-control mechanisms." (PMID 41009347, 2025). "For several cancers, small interfering RNA (siRNA)-mediated SHCBP1 knockdown diminishes tumor cell proliferation, induces apoptosis, and suppresses metastatic capabilities." (PMID 41009347, 2025). "This review is designed to systematically analyze the molecular mechanisms through which SHCBP1 modulates each of the principal cancer hallmarks." (PMID 41009347, 2025). "As expected, the expression of SHCBP1 was higher in cancer epithelial cells compared with normal luminal cells." (PMID 40799237, 2025). "Cancer epithelial cells exhibiting higher SHCBP1 expression display stronger interactions with stromal cells in the tumor microenvironment." (PMID 40799237, 2025). "SHCBP1 showed high expression levels in T cells, cancer epithelial cells, myeloid cells, and plasma cells." (PMID 40799237, 2025). "We divided cancer epithelial cells into high and low SHCBP1 clusters based on the median SHCBP1 expression." (PMID 40799237, 2025). "Through the integration of these elements within the established cancer hallmarks framework, this review aims to offer new perspectives on SHCBP1’s function in tumorigenesis and to underscore its therapeutic potential." (PMID 41009347, 2025). "The nucleoprotein SHCBP1 has been mentioned in multiple studies as a potential prognostic agent for many types of cancers." (PMID 40102990, 2025). "SHCBP1 is recognized as a multifunctional adaptor protein of considerable importance in cancer biology." (PMID 41009347, 2025). "The diverse oncogenic roles of SHCBP1, as discussed in previous sections, highlight its utility as a potential biomarker for multiple cancers." (PMID 41009347, 2025). "SHCBP1 is a critical signaling molecule, and several studies have explored its therapeutic significance in various types of cancer." (PMID 40657397, 2025). "As discussed in this review, SHCBP1 is consistently overexpressed in a variety of cancers and facilitates tumorigenesis by coordinating a broad range of oncogenic activities and modulating the hallmarks of cancer." (PMID 41009347, 2025). "Here, we analyze the mechanistic functions of SHCBP1 in these processes and examine its involvement in the canonical hallmarks of cancer." (PMID 41009347, 2025). "The stabilized SHCBP1 protein subsequently activates β-catenin signaling, which elevates glutathione peroxidase 4 expression and enhances cancer cell survival under oxidative stress." (PMID 41009347, 2025). "Collectively, these findings are consistent with pan-cancer analyses indicating SHCBP1 as a contributor to immune evasion and therapeutic resistance." (PMID 41009347, 2025).
cancer (continued). "More broadly, SHCBP1 depletion by siRNA or shRNA uniformly disrupts cell cycle progression, increases apoptosis, and attenuates invasiveness across multiple cancer models." (PMID 41009347, 2025). "We found that cancer epithelial cells with elevated SHCBP1 expression exhibited a strong interaction with stromal cells through the EGF, VEGF, IGFBP, CypA, GRN, and PTN signaling pathways." (PMID 40799237, 2025). "The important role of SHCBP1 in various oncogenic and immunomodulatory pathways highlights its value as a sensitizing target for combination cancer therapies." (PMID 41009347, 2025). "This section reviews data on the clinical significance of SHCBP1 expression, utilizing public cancer databases, bioinformatic results, and analyses of patient tissue specimens." (PMID 41009347, 2025). "Among various emerging regulatory proteins, SHC SH2-domain binding protein 1 (SHCBP1) has garnered increasing attention due to its diverse functions in cancer biology." (PMID 41009347, 2025). "These complex post-transcriptional mechanisms permit the rapid modulation of SHCBP1 levels according to urgent cellular needs, particularly during cancer progression." (PMID 41009347, 2025). "In general, the online public databases and LAUD specimens from two hospitals showed high SHCBP1 expression in cancer tissues, and the expression was closely correlated with patient survival and tumour proliferation." (PMID 38365687, 2024). "Many studies have confirmed that SHCBP1, as a proto-oncogene, is abnormally highly expressed in a variety of malignant tumors 14-15." (PMID 38021148, 2023). "Pan-cancer analysis was conducted to determine SHCBP1 expression levels in normal and tumor tissues using the TIMER and GTEx databases." (PMID 36920183, 2023). "Using a combination of CIBERSORT and XCELL algorithms, we found that SHCBP1 expression was positively correlated with CD8+ T cell infiltration in 12 types of cancer but negatively in 5 kinds of cancer." (PMID 36920183, 2023). "Recently, a growing number of studies have shown that SHCBP1 promotes tumorigenesis and progression of human tumors and is closely related to cancer prognosis." (PMID 36920183, 2023). "Previous research has shown that the level of SHCBP1 mRNA is markedly increased in several cancer cell lines and can promote tumorigenesis and development." (PMID 38021148, 2023). "Aberrant expression of SHCBP1 is involved in the occurrence, development, metastasis and prognosis of cancer, suggesting that SHCBP1 has potential value in terms of biomarkers and therapeutic targets." (PMID 36920183, 2023). "This comprehensive analysis highlights the multifaceted role of SHCBP1 and reveals its potential molecular mechanisms in generalized cancers." (PMID 36920183, 2023). "SHCBP1 has been previously reported as an immune-related biomarker for cancer diagnosis and prognosis and a potential therapeutic target for tumor immunotherapy." (PMID 38035071, 2023). "EGF/EGFR activation causes the detachment of SHC-binding protein 1 (SHCBP1) from SHC adapter protein 1 (SHC1), which subsequently translocates into the nucleus and promotes cancer development via multiple signaling pathways." (PMID 35013128, 2022). "EGF-induced nuclear localization of SHC Binding and Spindle Associated 1 (SHCBP1) activates β-catenin signaling by enhancing the CBP/β-catenin interaction and promotes cancer progression." (PMID 33827580, 2021). "Previous studies have found that SHCBP1 acts as a cancer-promoting gene in a variety of tumors, which is consistent with our findings." (PMID 32351983, 2020). "Additionally, the signaling pathways involved in the cell communications between the cancer epithelial cells and stromal cells differed regarding different SHCBP1 expression levels." (PMID 40799237, 2025). "Despite recent significant advancements, there remains a lack of a comprehensive overview that delineates SHCBP1’s multifaceted roles in relation to the hallmark features of cancer." (PMID 41009347, 2025).
cancer (continued). "Recent pan-cancer analyses identified SHCBP1 as an important factor in immune evasion." (PMID 41009347, 2025). "SHCBP1 expression levels and clinical relevance across various cancer types." (PMID 41009347, 2025). "Moreover, increased SHCBP1 expression is significantly linked to reduced overall survival, likely via alteration of the immunosuppressive TME in most cancers." (PMID 41009347, 2025). "Elucidating these regulatory circuits could provide new therapeutic strategies by enabling targeted intervention in SHCBP1 or its downstream effectors in cancer." (PMID 41009347, 2025). "According to multiple pan-cancer analyses, SHCBP1 expression is also positively associated with TMB, MSI, immune cell infiltration values, and the expression of immunosuppression-related genes, such as TGFBR1, PD-L1, and TGFB1 in various cancers." (PMID 41009347, 2025). "Further investigations using metabolic flux analysis, mitochondrial stress tests, and isotope tracing will be essential to determine whether SHCBP1 directly contributes to metabolic reprogramming in cancers." (PMID 41009347, 2025). "In addition, analysis using the Genomics of Drug Sensitivity in Cancer (GDSC) database indicates that elevated SHCBP1 in patients contributes to resistance against multiple chemotherapies." (PMID 41009347, 2025). "In this study, we explored and verified the potential roles of SHCBP1 in cancer development and progression via pan-cancer analysis, focusing on expression, prognosis, genetic alterations, protein phosphorylation, immune infiltration, and other relevant cellular processes." (PMID 36920183, 2023). "High expression of SHCBP1 was correlated with tumor pathological stage in several cancers." (PMID 36920183, 2023). "Interestingly, the microenvironment and immune scores showed similar correlations with SHCBP1 expression in pan-cancers other than in BRCA." (PMID 36920183, 2023). "This study is the first to systemically explore the roles of SHCBP1 in pan-cancer." (PMID 36920183, 2023). "Additionally, to investigate SHCBP1’s influence on the tumor microenvironment, the relationship between SHCBP1 expression and immune cell infiltration was investigated in different cancers." (PMID 36920183, 2023). "Furthermore, we evaluated the prognostic value of SHCBP1 in OS, showing that high SHCBP1 expression (H-score ≥ 70) correlates with a shorter OS time in cancer patients who received trastuzumab-based therapy." (PMID 33990570, 2021). "Interestingly, we observed that upregulation of SHCBP1 per se led to nuclear redistribution and β-catenin activation as well, and further experiments were performed to examine the significance of SHCBP1 upregulation in the development of cancer cell stemness." (PMID 30177836, 2019). "Although SHCBP1 is indicated to be overexpressed in several kind of cancers, it has not been associated with SS." (PMID 27572315, 2016). "Overall, these findings establish SHCBP1 as a therapeutically actionable target whose genetic suppression may enhance the effectiveness of standard chemotherapy and immunotherapy strategies across a broad spectrum of cancers." (PMID 41009347, 2025). "However, a comprehensive pan-cancer study of SHCBP1 has yet to be reported in human cancers." (PMID 36920183, 2023). "However, despite SHCBP1 being extensively studied in vitro previously, SHCBP1’s role in pan-cancer remains unclear." (PMID 36920183, 2023). "Accordingly, SHCBP1 may serve as a potential prognostic marker in certain cancers." (PMID 36920183, 2023). "Kaplan–Meier Plotter analysis indicated that low SHCBP1 expression correlated with better OS in breast (P=1.5e-06, HR=1.59 [1.31–1.92]), lung (P=3.2e-10, HR=1.5 [1.32–1.71]), ovarian (P=0.00025, HR=1.29 [1.13–1.48]), and liver (P=8e-04, HR=1.8 [1.27–2.54]) cancers." (PMID 36920183, 2023). "SHCBP1 is reported to activate MAPK/ERK/MEK through Shc, Grb2, Sos, and Kras signaling pathways in cancer cells." (PMID 40157910, 2025).